KRT71 (keratin 71)
Description:
Plays a central role in hair formation. Essential component of keratin intermediate filaments in the inner root sheath (IRS) of the hair follicle.
Synonyms: K6IRS1; KRT6IRS1; KRT6IRS; HYPT13
Tractability: PROTAC: ubiquitination databases record sites on it.
Gene: Protein-coding gene on chromosome 12 (52,543,909 to 52,553,145, reverse strand). Ensembl gene ENSG00000139648.
Subcellular location: Cytoplasm, cytoskeleton
Pathways (Reactome):
Developmental Biology: Formation of the cornified envelope; Keratinization
Gene Ontology:
Molecular function: protein binding; structural constituent of skin epidermis
Biological process: hair follicle morphogenesis; intermediate filament organization; keratinization
Cellular component: extracellular exosome; keratin filament; cytosol; cytoskeleton
Genetic constraint (gnomAD): Loss-of-function variants: 40 observed, 46.67 expected, observed/expected ratio (o/e) 0.86, 90% interval 0.67 to 1.12. The upper end of that interval is the gene's LOEUF score, 1.12, which puts it in group 4 of 6, group 1 being the genes least tolerant of losing a copy. Missense variants: 691 observed, 687.64 expected, observed/expected ratio (o/e) 1, 90% interval 0.94 to 1.07. Synonymous variants: 285 observed, 284.84 expected, observed/expected ratio (o/e) 1, 90% interval 0.91 to 1.1.
Homologues: Orthologues: chimpanzee KRT71 (99% identical), macaque KRT71 (98% identical), pig KRT71 (94% identical), rat Krt71 (92% identical), mouse Krt71 (91% identical), guinea pig KRT71 (91% identical), rabbit KRT71 (89% identical). Paralogues in human: KRT73 (84% identical), KRT74 (75% identical), KRT72 (72% identical), KRT3 (61% identical), KRT76 (60% identical), KRT5 (59% identical), KRT1 (58% identical), KRT2 (58% identical), KRT4 (58% identical), KRT6A (58% identical), KRT6B (58% identical), KRT75 (58% identical), and 56 more.
Diseases named in the same sentence as KRT71 in open-access papers:
KRT71 is named in the same sentence as 15 diseases in open-access papers, as found by Europe PMC text mining. Sharing a sentence is not in itself a finding about the gene and the disease. The quoted sentences say what the papers report.
hypotrichosis (6 papers, 2021 to 2025). A congenital condition, usually due to genetic aberrations, that is characterized by a lack of hair growth on the head and/or body. "The loss of function or mutations in the KRT71 gene may also bring about underdevelopment of the inner root sheath and recessive congenital hypotrichosis in Hereford cattle." (PMID 40941372, 2025). "Specifically, KRT75, KRT71, and KRT25 (which were found to be increased in both gene sequencing and qPCR analysis) are involved in hair and nail development, with mutations in these genes linked to conditions such as wooly hair and hypotrichosis." (PMID 40843897, 2025). "Pathogenic variants in KRT71 have previously been reported to be responsible for ADWH with hypotrichosis, but not LAHS." (PMID 40282419, 2025).
Hypotrichosis 13 (2 papers, 2023). "In addition, some paralog genes Krt25, Krt27, Krt72, Krt75, and Krt85, which also participate in the formation of keratin intermediate filaments in the IRS, could be related to Woolly Hair, Autosomal Recessive 3, and Hypotrichosis 8, which were significantly decreased in Krt71–KO mice." (PMID 37443815, 2023).
hypotrichosis 8 (2 papers, 2023 to 2025). Any hypotrichosis in which the cause of the disease is a mutation in the LPAR6 gene. "Moreover, relevant studies have discovered that mutations in the KRT71 and KRT74 genes might result in the symptoms of Hypotrichosis simplex (HS) and wooly hair (WH)." (PMID 40941372, 2025).
alopecia (1 paper, 2019). Hair loss usually from the scalp. "In reduced coat 3 (Rco3) mice carrying an autosomal recessive variant in Krt71 progressive alopecia develops due to alterations in the keratinization of the IRS and subsequent structural defects in the HSs." (PMID 30794648, 2019).
Brachycephaly (1 paper, 2019). An abnormality of skull shape characterized by a decreased anterior-posterior diameter. "A few of these loci, such as CACNA2D3 and MSRB3, have been previously implicated in human reproductive pathologies, whereas others have been associated with domestication-related traits, including brachycephaly (SMOC2) and coat curl (KRT71)." (PMID 31263560, 2019).
hair disorder (1 paper, 2021). "The loss-of-function variant most likely results to nonoccurrence of KRT71 during hair shaft molding, explaining the hair disorder." (PMID 34356054, 2021).
Male-pattern baldness (1 paper, 2023). "Studies have highlighted the pivotal role of KRT71 in hair formation, as it is involved in abnormal hair follicle morphology, focal hair loss, Male-pattern baldness, and abnormal hair cortex morphology." (PMID 37990155, 2023).
periodontitis (1 paper, 2015). An acute or chronic inflammatory process that affects the tissues that surround and support the teeth. "The two most down-regulated genes in periodontitis were keratin 71 (KRT71) and SP7 (fold change <−10 in both cases), of which the latter was also identified by the OPLS-DA." (PMID 26686060, 2015).
cancer (1 paper, 2020). A tumor composed of atypical neoplastic, often pleomorphic cells that invade other tissues. "KRT71 is a member of the Keratin family, which may be related to hair follicle morphogenesis, but its relationship with cancer has not been reported yet." (PMID 33335850, 2020).
tumor (1 paper, 2020). "Among them, four genes, including APOL1, CCL17, RBP4, and KRT71 were selected in real-time PCR experiments between tumor samples and normal samples, which were found to be consistent with the expression trend in low- and high-risk groups." (PMID 33335850, 2020).
KRT71 also shares sentences with these, for which no sentence is quoted: Familial Woolly Hair Syndrome (2 papers); alopecia areata (1); fibrolamellar carcinoma (1); mastitis (1); skin inflammation (1).